ENSG00000222185
Synonyms: LOC124903421
Gene: Small nucleolar RNA gene on chromosome 14 (100,998,467 to 100,998,541, forward strand). Ensembl gene ENSG00000222185.
Gene Ontology:
Biological process: RNA processing
Cellular component: nucleolus
Homologues: Paralogues in human: SNORD113-8 (73% identical), SNORD113-7 (71% identical), SNORD114-12 (67% identical), SNORD114-13 (67% identical), SNORD113-3 (65% identical), SNORD113-4 (65% identical), SNORD113-5 (65% identical), SNORD114-14 (65% identical), SNORD114-17 (65% identical), SNORD114-19 (65% identical), SNORD114-21 (65% identical), SNORD113-6 (64% identical), and 27 more.